TRPM2 (transient receptor potential cation channel subfamily M member 2)
Diseases named in the same sentence as TRPM2 in open-access papers (continued):
Sharing a sentence is not in itself a finding about the gene and the disease.
inflammation (4 papers, 2012 to 2021). Aberrant reaction of the microcirculation characterized by movement of fluid and leukocytes from the blood into extravascular tissues. "Consistently, SiNPs-induced pulmonary inflammation was prevented in TRPM2 deficient mice." (PMID 32513195, 2020). "A recent study has drawn attention to the role of the TRPM2 channel in endothelial barrier dysfunction, pulmonary inflammation and lung damage induced by uPMs of 100–300 nm collected from ambient air." (PMID 34063677, 2021). "A distinctive or additional TRPM2-mediated cellular mechanism have been proposed for silico nanoparticles-induced pulmonary inflammation and lung tissue damage in adult male C57BL/6 mice in another recent study." (PMID 34063677, 2021). "More significantly, our study shows the TRPM2 channel as a key mechanism for SiNPs-induced pulmonary inflammation and lung injury." (PMID 32513195, 2020). "The ROS/PARP/TRPM2 signaling is critical in SiNPs-induced pulmonary inflammation, providing novel mechanistic insights into NPs-induced lung injury." (PMID 32513195, 2020). "Our findings suggest TRPM2 cation channels as a potential target for treating autoimmune CNS inflammation." (PMID 23077651, 2012). "Hence, this model might not be suitable to test for TRPM2 as a therapeutic target for allergen-induced airway inflammation or the channel itself might not play a significant role in allergen-mediated inflammation." (PMID 23631390, 2013). "In conclusion, although TRPM2 appears to be involved in certain inflammatory responses that are mediated by monocyte-dependent chemokine production in response to ROS, this inflammatory mechanism may not dominate the mechanisms engaged in the OVA-mediated severe airway inflammation model." (PMID 23631390, 2013).
metabolic disease (4 papers, 2023 to 2025). A congenital disorder (due to inherited enzyme abnormality) or acquired (due to failure of a metabolically important organ) disorder resulting from an abnormal metabolic process. "This review examines the role of TRPM2 channels in oxidative stress-associated cardiovascular and metabolic diseases." (PMID 40867637, 2025). "Although TRPM2 channels have been implicated in most cardiovascular and metabolic diseases, early insights into the underlying signalling mechanisms are only just beginning to emerge." (PMID 40867637, 2025). "However, during oxidative stress, TRPM2 overactivation leads to Ca2+ overload, which is linked to several ROS-driven diseases, including cardiovascular and metabolic diseases." (PMID 40867637, 2025). "In both studied examples (endothelial cells and β-cells), TRPM2-mediated Ca2+ influx caused extensive structural damage to the mitochondrial network, leading to functional decline and increased ROS production—a hallmark of cardiovascular and metabolic diseases, as well as ageing." (PMID 40867637, 2025). "Since ROS activation of the TRPM2 channel is central to most cardiovascular and metabolic diseases, it is essential to review the sources and dynamics of ROS and the mechanisms by which they are amplified in disease conditions." (PMID 40867637, 2025). "Given the interconnected nature of cardiovascular and metabolic diseases, it is likely that the TRPM2-driven signalling mechanism is conserved between these diseases." (PMID 40867637, 2025). "Among these calcium channels, the TRPM2 channel is of particular interest due to its potent activation by ROS and its implication in numerous NCDs, including neurodegenerative, cardiovascular, and metabolic diseases, as well as cancer." (PMID 40867637, 2025). "Further studies are required to investigate whether pharmacological TRPM2 activation may represent a new therapeutic strategy for the treatment of metabolic diseases, aimed at improving thermogenic capacity and activity of WAT and BAT." (PMID 38390373, 2023). "Among TRP channels, TRPM2 (Transient Receptor Potential Melastatin 2) emerges as particularly important due to its direct sensitivity to OS-generated molecules and its established role in promoting OS-related damage in numerous cardiovascular, neurodegenerative, and metabolic disease models." (PMID 40722879, 2025). "Given that TRPM2 and NOX-2 are involved in a wide range of NCDs, including some cardiovascular and metabolic diseases, this mechanism may be shared by many diseases." (PMID 40867637, 2025).
brain diseases (3 papers, 2020 to 2025). "Given its role in sensing and responding to oxidative stress, many research groups investigated the potential role of TRPM2 in oxidative stress-mediated brain diseases." (PMID 37576339, 2023). "Collectively, these results highlight the therapeutic potential of TRPM2 and suggest the inhibition of TRPM2 as promising strategy to counteract the deleterious effects of in brain diseases." (PMID 37576339, 2023). "In addition, brain disease-induced ROS production triggers TRPM2 activation, leading to calcium influx from the extracellular space, and finally triggers cell death cascades that include PARP-1/PARG and caspase-dependent cell-death pathways." (PMID 32825703, 2020).
immune disease (3 papers, 2015 to 2023). "On the other hand, the genes ITGB7, CSAD, and TRPM2 are associated with immune system diseases that accompany skin deficiencies." (PMID 37990155, 2023). "As we know, TRPM2 has a protective role in the regulation of inflammatory disorders/immune disease." (PMID 29250536, 2017).
TRPM2 also shares sentences with these, for which no sentence is quoted: dementia (3 papers); adenocarcinoma (2); autism spectrum disorder (2); Autoimmunity (2); breast (2); depression (2); ischemia reperfusion injury (2); Kidney Chromophobe (2); lymphoma (2); atrial fibrillation (1); autoimmune disorders (1); cerebral infarction (1); channelopathies (1); chronic fatigue syndrome (1); chronic kidney disease (1); Cirrhosis (1); colorectal adenocarcinoma (1); Coronary Heart Disease (1); Crohn disease (1); diffuse large B-cell lymphoma (1); ductal carcinoma (1); endometrial carcinoma (1); experimental autoimmune encephalomyelitis (1); fibromyalgia (1); Huntington disease (1); infectious disease (1); inflammatory bowel disease (1); Intellectual disability (1); invasive breast carcinoma (1); Jaundice (1).
A further 27 diseases each share a sentence with TRPM2 in 1 paper.